SETDB1 (SET domain bifurcated histone lysine methyltransferase 1)
Diseases named in the same sentence as SETDB1 in open-access papers (continued):
Sharing a sentence is not in itself a finding about the gene and the disease.
cancer (continued). "Although the study by Zhang and colleagues focused mainly on the effect of KDM5B knockout on the anti-cancer immune response, the authors showed that KDM5B recruits and stabilizes SETDB1 to silence its targets, including REs." (PMID 39519018, 2024). "SET domain bifurcated 1 (SETDB1) is an important histone 3 lysine 9 (H3K9) methyltransferase, which is found to be abnormally expressed in several types of cancers." (PMID 39583200, 2024). "The increased SETDB1 expression was then responsible for facilitating EMT by activating the Wnt/β-catenin pathway, contributing to cancer progression." (PMID 39703687, 2024). "In summary, our results demonstrate that SETDB1‐mediated MCT1 methylation is a critical factor in CRC, and MCT1 K473 tri‐methylation has the potential to be a predictive marker for cancer outcome." (PMID 37541664, 2023). "More work is needed to characterize the synthetic lethal interaction between CHD4 and SETDB1 in TNBC and other cancers." (PMID 37970920, 2023). "The 1q+ tumors of EX3 share overexpression of seven cancer genes e.g., BCL9 and SETDB1, whilst EX1 1q+ tumors share only MDM4 overexpression and overexpress fewer cancer genes overall." (PMID 36230794, 2022). "A significant positive correlation was observed between SETDB1 expression and CNV in various cancers." (PMID 35656340, 2022). "Thus, the role of SETDB1 in cancer may depend on its type and stage." (PMID 36582533, 2022). "Furthermore, SETDB1 may be a potential therapeutic target for cancer treatment." (PMID 35656340, 2022). "For example, DPY30 was significantly positively correlated with SETD1A, SETDB1 and RBBP5, which have been reported to promote the occurrence and progression of cancers." (PMID 34090418, 2021). "Enforced expression of GATA3 in HCT116 cells inhibited a series of cancer-promoting proteins, DNMT1, SETD1A, SETDB1, FOXM1, MYC, and MSI1." (PMID 34595169, 2021). "Using UALCAN, an online cancer database and specimens of CRC patients, we found the expression of SETDB1 was upregulated in CRC." (PMID 32393761, 2020). "To further confirm the expression of SETDB1 in CRC, we examined the expression of SETDB1 in tumor and adjacent normal tissues of 60 CRC patients, the result of qRT-PCR showed that SETDB1 was highly expressed in cancer tissues compared to the controls." (PMID 32393761, 2020). "SETDB1, a histone H3K9 methyltransferase, has been reported to be upregulated in a variety of tumors and promotes cancer development." (PMID 32393761, 2020). "The overexpression of SETDB1 was significantly related to HCC progression, cancer invasiveness, and poor survival of HCC patients." (PMID 30503969, 2019). "Our subgroup analyses for ADC and SCC showed higher SETDB1 mRNA levels in ADC as compared to SCC, while SETDB1 expression in both cancer subtypes was still significantly higher than in normal lung tissues." (PMID 31398867, 2019). "Microarray, qRT-PCR and protein expression data confirmed the up-regulation of histone methyltransferases (SETDB1 and SETDB2) which contribute to the accumulation of H3K9me3 concomitantly in the different cancer types." (PMID 29492189, 2018). "Many epigenetic regulators exert cross‐talk with DNA methylation including SETDB1 47, which can act independently or in concert with KAP1 25 and which itself has a reported role in innate immune control in cancer cells." (PMID 30061100, 2018). "Among them, SETDB1, SUV39H1 and EZH2 are reported to be frequently over-expressed in various cancers, such as GCs, those of which functions are shown as oncogenic activities." (PMID 27572307, 2016). "In particular, we identified the epigenetic regulatory genes NSD3, SETDB1, YEATS4, and BRD4 as putative amplified cancer drivers in several cancer types." (PMID 24874471, 2014). "While the amplifications of SETDB1 and BRD4 have been previously identified and their roles in cancer have been well-studied, less is known about the functions of YEATS4 and NSD3 in cancer." (PMID 24874471, 2014).
cancer (continued). "On the other hand, enzymes that deposit repressive histone marks, such as the H3K9 trimethylases SETDB1 or SUV39H1/2, and the H3K27 trimethylase EZH2 are overexpressed in most cancer types studied." (PMID 25484917, 2014). "In the cancer cell line C33a, MCAF1, MBD1, and SETDB1 co-localize at the H3K9me3-containing heterochromatin region." (PMID 23935871, 2013). "Future experiments to investigate SETDB1 and SUVH31 expressions in odontogenic lesions may be beneficial as these enzymes are now in the clinical trials for various cancers." (PMID 39510524, 2025). "The Cysteine/methionine metabolism pathway, prominently featured by S-Adenosylmethionine and S-Adenosylhomocysteine metabolites, could be influenced by pan-cancer oncogenes EZH2 and SETDB1." (PMID 39982908, 2025). "We note this narrower CNA segment does not include the MDM4 oncogene, which is located at 1q32.1, thus other genes must be driving this recurrent genetic change in CNA-PC86, with possible candidates being known cancer genes BCL9 (1q21.2), ARNT (1q21.3), SETDB1 (1q21.3), or SF3B4 (1q21.2)." (PMID 41023738, 2025). "Second, recent studies on SETDB1 have highlighted its important role in regulating cancer through methylation of non-histone proteins, which further expands the downstream mechanism of SETDB1." (PMID 39583200, 2024). "Ablation of SETDB1 in this study did not induce the antiviral IFN pathway but unleashed the expression of retroelement-encoded MHC I peptides, both in mouse and human cancer cells." (PMID 39519018, 2024). "Interestingly, high levels of SETDB1 mRNA were found to persist in all stages of cancer in NSCLC patients, suggesting that SETDB1 has different roles at different stages of tumorigenesis." (PMID 39583200, 2024). "The data suggest that unlike cell cycle-related pathways, which are upregulated in hypoxic cancer irrespective of SETB1, activation of inflammatory and immune response functions is linked to low expression of SETDB1 in hypoxia." (PMID 37850636, 2023). "Recent studies have shown that in a variety of cancers, multiple epigenetic modifiers, such as SET domain bifurcated histone lysine methyltransferase 1 (SETDB1) and lysine‐specific demethylase 1A (LSD1), play critical roles in regulating the expression of endogenous antigens and immune responses." (PMID 37712124, 2023). "In addition, SETDB1-mediated expression of FOSB/AP-1, a common target gene, is involved in diverse cancers." (PMID 35497876, 2022). "Even though an exact mechanism of action of SETDB1 in cancer has not been revealed, recent reports have established that SETDB1 is involved in gene silencing, methylation of Akt, suppression of tumor-intrinsic immunogenicity, and so on." (PMID 35372573, 2022). "Apart from targeting Skp2, development of specific inhibitors targeting Akt upstream regulators, such as TRAF6, SETDB1 and JMJD2A, may also serve as a novel and innovative strategy for eradicating hyperactive Akt-driven human cancers." (PMID 36180910, 2022). "According to our findings, increased expression of SETDB1 has a significantly negative correlation with immunoinhibitor and immunostimulator in most cancers." (PMID 35656340, 2022). "Since most of the chromatin regulators described here (LSD1, PRMT7, SETDB1, KDM5B, and ATF7IP) converge functionally, it will be crucial to identify additional cancer-specific factors the targeting of which may be less toxic." (PMID 36497341, 2022). "Moreover, SETDB1 was also found to repress the expression of radiation-induced ERVs, and SETDB1 deletion potently enhanced ERV expression and increased type I interferons, promoting antitumour immunity and sensitizing cancer radiotherapy." (PMID 36582533, 2022). "Moreover, in cancers, transposable elements and immune clusters were discovered to be silenced by SETDB1-dependent H3K9 methylation, which identifies SETDB1 as a negative regulator for tumour-intrinsic immunity." (PMID 34299035, 2021).
cancer (continued). "Further studies are warranted to know whether the oncogenic characteristics of SETDB1 and SETDB2 are universal for all cancers or just specific to particular cancer type." (PMID 31245293, 2019). "Therefore, despite the limitations, we assume that the results of our study on DNA methylation of apoptosis-associated genes suggest the possible involvement of five genes (SETDB1, TWIST1, HDAC1, SP1, and GRIA2) in the phenomenon of inverse comorbidity of neurodegenerative diseases and cancers." (PMID 40843670, 2025). "However, SETDB1 expression is relatively stable across tissues and ages, suggesting another mechanism that spreads and intensifies DNA methylation in chr19 ZFP genes in cancer and aging." (PMID 38904842, 2024). "This suggests that SETDB1‐mediated methylation of MCT1 is positively correlated with CRC patients’ overall survival time, and MCT1 methylation at K473 might be a potential predictive marker for cancer outcome." (PMID 37541664, 2023). "SET Domain, Bifurcated 1 (SETDB1) catalyzes the trimethylation of histone H3K9 (H3K9me3) and thereby promotes transcriptional silencing, the N-terminal of SETDB1 interacts directly with the plant homeodomain of DNMT3A and localizes to a silent promoter in cancer cells." (PMID 35463343, 2022). "Furthermore, SETDB1 has been involved in NSCLC progression through WNT–β-catenin pathway stimulation, and for these roles, it was nominated to be a therapeutic target to fight against numerous cancers." (PMID 36430577, 2022). "In addition to the PRC complex, several regulators of histone H3K9 methylation, such as the SET domain-containing histone methyltransferases SETDB1 and G9a (also known as euchromatic histone lysine N-methyltransferase 2, EHMT2), play important roles in regulating pluripotency and cancer stemness." (PMID 35455671, 2022). "Specifically, given the SETDB1–AKT axis (discussed in Section 6.1), there is great interest in examining the cooperation between protein kinases and histone methylases to mediate expression of oncogenes and immune genes to counteract the effects of cancer cells." (PMID 31405032, 2019). "Interestingly, Hep3B cells were insensitive to SETDB1 knockdown, suggesting that the SETDB1 expression level per se does not determine the cancer cell dependence." (PMID 26471002, 2015). "Besides LSD1, enzymes involved in histone lysine methyltransferases and lysine demethylases, such as SUV39H1 (KMT1A), SETDB1 (KMT1E), KDM4B, and KDM5A, have been found to be involved in the DDR, suggesting that their inhibitors have combination therapy potential with PARPi for cancer treatment." (PMID 37973845, 2023). "SETDB1 expression was positively correlated with TMB in BLCA, BRCA, LGG, LUAD, and STAD, while negatively correlated with TMB in THCA and UCS, but did not correlate with TMB in other cancers." (PMID 35656340, 2022). "However, in contrast to what is known about the role of SETDB1 in repressing LINE-1s in DTPs, it is currently not known if KDM5 functions through suppression of the viral mimicry response to promote survival of cancer cells during otherwise lethal drug exposures." (PMID 35602594, 2022).
tumor (99 papers, 2011 to 2026). "Overall, these data demonstrate that high SETDB1 expression is linked to both mutational burden and molecular programs associated with tumor aggressiveness and poor clinical outcomes in HCC." (PMID 41493679, 2026). "Recent analyses in HCC reveal that SETDB1 is overexpressed and strongly associated with advanced disease features, such as tumor microsatellite formation and metastasis." (PMID 41493679, 2026). "We also observed that the Coulouarn_temporal_TGFb1_signature, a hallmark of tumor progression and dedifferentiation, was specifically enriched in the SH group, reinforcing the association between SETDB1 expression and aggressive tumor phenotypes." (PMID 41493679, 2026). "SETDB1 is notably overexpressed in aggressive types of diseases and is often implicated in the epigenetic regulation of tumor progression and metastasis." (PMID 39945463, 2025). "Amplification of SETDB1 in human tumors has been associated with immune evasion, while the loss of SETDB1 can trigger anti-tumor immune responses." (PMID 40739089, 2025). "SETDB1 overexpression is associated with aggressive tumor behavior, including lymph nodes and/or distant metastases." (PMID 40427015, 2025). "Their observations revealed that the loss of Setdb1 elevated ICB treatment efficacy by sensitizing tumor cells." (PMID 39519018, 2024). "SETDB1 is enriched in many human cancers and its overexpression is associated with suppressed anti-tumor immune activity and resistance to immune checkpoint blockade." (PMID 35515106, 2022). "The main underlying mechanism is H3K9me3 deposition by SETDB1 on tumour-suppressive genes, retrotransposons, and immune genes." (PMID 36582533, 2022). "Among the mutations validated by exome and targeted sequencing in MPM tumor samples, we found that SETDB1 had a nonsense mutation (Y249X)." (PMID 26824986, 2016). "Given the genomic complexity of HCC, which typically harbors 35 to 80 somatic mutations in coding regions per tumor, we assessed whether SETDB1 expression was associated with key driver mutations." (PMID 41493679, 2026). "Recently, the utility of SETDB1 as a potent therapeutic target in combination with immune checkpoint blockade was highlighted based on the finding that SETDB1 inactivation generated TE-encoded antigens to boost tumor immunogenicity." (PMID 37850636, 2023). "The amplification of SETDB1 in human tumors is significantly associated with immune exclusion and tumor progression, but its biological and functional role or contribution to tumor prognosis is unknown." (PMID 35656340, 2022). "The opposing expression of PD-L1 upon SETDB1 loss in these two studies may be attributed to the distinct tumour types and regulatory mechanisms." (PMID 36582533, 2022). "SETDB1 depletion in mouse tumours derepresses immunostimulatory genes and TE-encoded retroviral antigens and MHCI peptides, which will increase CD8+ T cells and p15E-specific CD8+ T cells expressing canonical cytotoxicity genes, triggering cytotoxic T cell responses and sensitizing tumours to ICB." (PMID 36582533, 2022). "Interestingly, recent reports have implicated the histone methyltransferase SETDB1 in suppression of TEs and tumour immunogenicity, including effects in hypomethylated cell line models." (PMID 35388081, 2022). "However, SETDB1 has also been strongly implicated in the pathogenesis of multiple diseases, including neurological disorders, cardiovascular, gastrointestinal diseases and most notably, tumor development and progression." (PMID 34440561, 2021). "Moreover, SETDB1 mRNA levels were higher in tissues from NSCLC patients compared to non-tumor tissues, and this increase was associated with advanced grade NSCLC tumors, shorter overall survival in NSCLC patients and shorter disease-free survival in NSCLC patients in stage I." (PMID 31398867, 2019).
tumor (continued). "The tumor microenvironment also contributes to SETDB1 accumulation, particularly through hypoxia, a well-established driver of CSC maintenance." (PMID 41493679, 2026). "Differential expression analysis revealed a significant upregulation of SETDB1 mRNA in tumor tissues compared to adjacent normal liver tissues." (PMID 41493679, 2026). "Taken together, our data showing the strong correlation between SETDB1 expression, stemness features, and tumor aggressiveness highlight SETDB1 as a compelling therapeutic target in HCC." (PMID 41493679, 2026). "This dual regulation suggests that SETDB1 reinforces tumor plasticity not only through chromatin remodeling but also by orchestrating a pro-oncogenic miRNA environment." (PMID 41493679, 2026). "Tumor radiosensitivity appears to be inversely correlated with SETDB1 expression, through mechanisms that influence cellular immune infiltration, including T cells, macrophages, NK cells, and dendritic cells." (PMID 39945463, 2025). "In colorectal cancer, SETDB1 drives tumor development and proliferation by downregulating the tumor suppressor factor p21 and promoting EMT regulation." (PMID 39945463, 2025). "Beyond its immunological implications, SETDB1 overexpression fosters tumor growth and metastasis via transcriptional silencing of tumor suppressor genes through histone regulation and activating oncogenic signaling by non‐histone regulation." (PMID 39764697, 2025). "One of the most prominent regulation of immune response mediated by SETDB1 is its ability to prevent tumor cells from evading innate immune sensing by limiting endogenous retrotransposon expression." (PMID 39945463, 2025). "Analysis of tumor heterogeneity using inferHeterogeneity revealed MATH scores > 50 in patients possessing NDUFS1 and SETDB1 mutations, thus showing high intratumoral heterogeneity (p = 0.01)." (PMID 41503337, 2025). "Recent studies have highlighted SETDB1 as a key player in tumor immune evasion and immune checkpoint therapy resistance." (PMID 39764697, 2025). "It has also been shown that the cytoplasmic expression of SETDB1 correlates significantly with a higher methylation frequency and suppressed expression of the p16 tumor suppressor." (PMID 40427015, 2025). "Consistently, different studies on lung, skin, bladder, ovary, colon, and other tumor types show that blocking of SETDB1 and other H3K9me3-related proteins sensitizes tumors to ICB treatment." (PMID 39519018, 2024). "Recent studies have shown that the expansion of SETDB1 in human tumors plays a crucial role in allowing tumor immune escape and resisting ICB." (PMID 39583200, 2024). "SET domain bifurcated histone lysine methyltransferase 1(SETDB1) acts as an oncogene in a variety of tumours." (PMID 38317200, 2024). "SETDB1 suppresses the intrinsic immunogenicity of tumours through epigenetic silencing and represents a candidate target for immunotherapy." (PMID 38317200, 2024). "Several recent studies have confirmed that SETDB1 plays as an oncogene and widely amplified and overexpressed in human tumours." (PMID 38317200, 2024).